PIK3R6 (phosphoinositide-3-kinase regulatory subunit 6)
Description:
Regulatory subunit of the PI3K gamma complex. Acts as an adapter to drive activation of PIK3CG by beta-gamma G protein dimers. The PIK3CG:PIK3R6 heterodimer is much less sensitive to beta-gamma G protein dimers than PIK3CG:PIK3R5 and its membrane recruitment and beta-gamma G protein dimer-dependent activation requires HRAS bound to PIK3CG. Recruits of the PI3K gamma complex to a PDE3B:RAPGEF3 signaling complex involved in angiogenesis; signaling seems to involve RRAS.
Synonyms: p84 PIKAP; p87PIKAP; C17orf38; FLJ34500; HsT41028; p87(PIKAP)
Tractability: Antibody: UniProt places it where antibodies can reach, with medium confidence; its Gene Ontology location is reachable by antibodies, with medium confidence; the Human Protein Atlas places it where antibodies can reach.
Gene: Protein-coding gene on chromosome 17 (8,802,722 to 8,867,686, reverse strand). Ensembl gene ENSG00000276231.
Subcellular location: Cytoplasm; Cell membrane
Subcellular location (Human Protein Atlas): Golgi apparatus; Nucleoplasm; Cytosol; Plasma membrane
Pathways (Reactome):
Signal Transduction: G beta:gamma signalling through PI3Kgamma; PI5P, PP2A and IER3 Regulate PI3K/AKT Signaling; PIP3 activates AKT signaling
Immune System: CD28 dependent PI3K/Akt signaling; Co-stimulation by ICOS
Disease: Constitutive Signaling by Aberrant PI3K in Cancer
Hemostasis: GPVI-mediated activation cascade
Metabolism: Synthesis of PIPs at the plasma membrane
Gene Ontology:
Molecular function: protein binding; 1-phosphatidylinositol-3-kinase regulator activity; 1-phosphatidylinositol-4,5-bisphosphate 3-kinase activity
Biological process: G protein-coupled receptor signaling pathway; positive regulation of angiogenesis; regulation of natural killer cell mediated cytotoxicity; immune response; positive regulation of MAP kinase activity; positive regulation of T cell differentiation
Cellular component: phosphatidylinositol 3-kinase complex, class IA; cytoplasm; cytosol; membrane; phosphatidylinositol 3-kinase complex; phosphatidylinositol 3-kinase complex, class IB; plasma membrane
Genetic constraint (gnomAD): Loss-of-function variants: 89 observed, 77.47 expected, observed/expected ratio (o/e) 1.15, 90% interval 0.97 to 1.37. The upper end of that interval is the gene's LOEUF score, 1.37, which puts it in group 5 of 6, group 1 being the genes least tolerant of losing a copy. Missense variants: 993 observed, 942.76 expected, observed/expected ratio (o/e) 1.05, 90% interval 1 to 1.11. Synonymous variants: 414 observed, 383.05 expected, observed/expected ratio (o/e) 1.08, 90% interval 1 to 1.17.
Homologues: Orthologues: chimpanzee PIK3R6 (99% identical), macaque PIK3R6 (95% identical), mouse Pik3r6 (83% identical), guinea pig PIK3R6 (82% identical), rat Pik3r6 (82% identical), pig PIK3R6 (82% identical), dog PIK3R6 (80% identical), rabbit PIK3R6 (78% identical), tropical clawed frog pik3r6 (44% identical), zebrafish pik3r6b (34% identical). Paralogues in human: PIK3R5 (24% identical).
Diseases named in the same sentence as PIK3R6 in open-access papers:
PIK3R6 is named in the same sentence as 20 diseases in open-access papers, as found by Europe PMC text mining. Sharing a sentence is not in itself a finding about the gene and the disease. The quoted sentences say what the papers report.
melanoma (3 papers, 2015 to 2023). A malignant, usually aggressive tumor composed of atypical, neoplastic melanocytes. "In addition, pik3r6 displays recurrent somatic mutations in human melanoma and would thus be considered a high priority target in future experiments designed to utilize drugs that target this gene in our melanoma fish and observe therapeutic outcomes." (PMID 26714172, 2015). "PIK3CG mutation and amplification are frequent in multiple malignancies, including 9–11% of melanomas and uterine, stomach and squamous cell lung cancers, while genetic alterations in PIK3R5 and PIK3R6 are prevalent in uterine cancer and melanoma, occurring in 4–8% of cases." (PMID 32630372, 2020).
histiocytic sarcoma (2 papers, 2021 to 2022). An aggressive malignant neoplasm with a poor response to therapy, usually presenting as stage III/IV disease. "The PI3K pathway gene PIK3R6 on canine chromosome 5 was observed strongly associated to histiocytic sarcoma in dogs, and upregulation of TNFIAP6 in chromosome 19 is considered a risk factor as well." (PMID 35875106, 2022). "The first includes variants in regulatory regions at the tumor suppressor PIK3R6 locus that are strongly associated with histiocytic sarcoma and likely confer risk for other hematopoietic cancers." (PMID 33983928, 2021). "Among the candidate variants identified herein, CFA5:33576022, located upstream of PIK3R6, emerged as particularly strong, demonstrating the lowest allele frequency in 232 breeds that are at low to zero risk for developing histiocytic sarcoma (1%)." (PMID 33983928, 2021). "The PI3K pathway gene PIK3R6 on chromosome 5 and upregulation of TNFIAP6 in chromosome 19 were observed strongly associated to histiocytic sarcoma in dogs." (PMID 35875106, 2022). "Candidate genes at both loci, PIK3R6 and TNFAIP6, have tumor suppressive and metastatic roles in other cancers, and mutations in members of the PI3K and tumor necrosis factor pathways have been identified in human histiocytic sarcoma and lymphoma tumors." (PMID 33983928, 2021).
asthma (1 paper, 2024). "The expression of HSPA1A, PIK3CG and PIK3R6 was associated with moderate asthma, while MAPK13 and MMP9 were associated with severe asthma." (PMID 39088141, 2024). "Among the genes involved in these important signaling pathways, HSPA1A, PIK3CG and PIK3R6 seemed to be associated with moderate asthma, while MAPK13 and MMP9 appeared to be associated with severe asthma." (PMID 39088141, 2024). "The expression of HSPA1A, PIK3CG and PIK3R6 in the same 10 and 4 pathways was then verified, while the expression of MAPK13 and MMP9 related to severe asthma was also confirmed." (PMID 39088141, 2024). "Overall, this study discovered a total of five genes, including HSPA1A, PIK3CG, PIK3R6, MAPK 13 and MMP9, as potential biomarkers of moderate or severe asthma." (PMID 39088141, 2024). "PIK3CG and PIK3R6, though having no known role in asthma, was verified in the present analysis as well as other published datasets, which were used as potential novel biomarkers or therapeutic targets." (PMID 39088141, 2024).
bipolar disorder (1 paper, 2023). A disorder of the brain that causes unusual shifts in mood, energy, activity levels and the ability to carry out day-to-day tasks. "A previous study found that IL5RA and PIK3R6 were upregulated in lithium-treated bipolar disorder patients." (PMID 37186582, 2023).
diabetes (1 paper, 2021). "Phosphoinositide-3-kinase regulatory subunit 6 (PIK3R6) has been shown to be upregulated in the diabetes rat model, which was associated with the development of type II diabetes in mice." (PMID 34650970, 2021).
glioma (1 paper, 2022). A benign or malignant brain and spinal cord tumor that arises from glial cells (astrocytes, oligodendrocytes, ependymal cells). "The Macro index comprised of PIK3R5, PIK3R6, ALOX5, ALOX5AP, and ALOX15B serves as a valid prognostic biomarker for gliomas, especially LGG." (PMID 36159811, 2022).
hemangiosarcoma (1 paper, 2021). "PIK3R6 was downregulated in B-cell lymphoma tumors from golden retrievers that harbored the CFA5:29 Mb hemangiosarcoma risk haplotype in this breed." (PMID 33983928, 2021).
hyperlipidemia (1 paper, 2025). "Therefore, PIK3R6 may serve as a molecular link between hyperlipidemia and ED through regulation of the PI3K/Akt pathway, potentially explaining the association between gene expression differences and ED phenotypes." (PMID 41291978, 2025).
ovarian carcinoma (1 paper, 2021). A malignant neoplasm originating from the surface ovarian epithelium. "Moreover, PIK3R6 has been demonstrated to promote the proliferative and migratory potentials in ovarian cancer cells." (PMID 34650970, 2021).
prostate carcinoma (1 paper, 2023). A carcinoma that arises from epithelial cells of the prostate gland. "The most strongly upregulated gene in RC43N that is annotated to RC43N 1α,25(OH)2D3-regulated NF region was PIK3R6, which recently was identified as a novel antigen in a clinical immunotherapy trial in advanced prostate cancer." (PMID 37082578, 2023).
rectum adenocarcinoma (1 paper, 2022). An adenocarcinoma arising from the rectum. "Finally, we predicted and verified 8 GRSDMs in adrenocortical carcinoma (ACC), rectum adenocarcinoma (READ), uveal Melanoma (UVM), thyroid carcinoma (THCA), and predicted 4 GRSDMs (F2RL3, DGKB, GRK5, PIK3R6) which were sensitive to 12 potential drugs." (PMID 35885996, 2022).
tumor (6 papers, 2021 to 2025). "In the CBX3-high expression group, increased in PIK3R6 expression levels were associated with score increases (EstimateScore, StromalScore, ImmuneScore) and decreases in tumor purity." (PMID 37674204, 2023). "PIK3R6 has a tumor suppressive role; knockdown increases PI3Kγ signaling and the potential for cells to metastasize." (PMID 33983928, 2021). "PIK3R6 is used in combination with ICB (atezolizumab) as one of the tumor vaccine antigens." (PMID 36866272, 2023). "This requires glucose uptake and energy sources for normal cellular response to stress and tumor growth, syndrome development, vascular changes, and megalocephaly (e.g., PIK3R1; PIK3CA; PIK3CG; PIK3CD; PIK3CB; PIK3R3; PIK3R2; PIK3R5; PIK3R6)." (PMID 41010006, 2025).
cancer (4 papers, 2021 to 2024). A tumor composed of atypical neoplastic, often pleomorphic cells that invade other tissues. "Here, they established a novel risk score model, according to which the PIK3R6 gene was predicted to have a poor prognosis, higher immune pathway activation, and cancer development." (PMID 38638111, 2024). "In order to verify reliable GRSDMs, 22 specific DNA methylation genes related to prognosis obtained in the training set were verified on 11 sets of GEO data, and 8 of the specific DNA methylation genes (DGRK, F2RL3, GRK5, NECAB2, OR1C1, OR2L13, OR6F1, and PIK3R6) had been verified in pan-cancer." (PMID 35885996, 2022). "PIK3R6 functions in the PI3K/Akt pathway, which is commonly dysregulated in cancer, in leukocytes." (PMID 33983928, 2021).
PIK3R6 also shares sentences with these, for which no sentence is quoted: gastric cancer (1 paper); glioblastoma (1); lymphoma (1); staphylococcus aureus infection (1); thyroid carcinoma (1); type II diabetes (1); uveal melanoma (1).